IL10 (interleukin 10)
Diseases named in the same sentence as IL10 in open-access papers (continued):
Sharing a sentence is not in itself a finding about the gene and the disease.
colitis (continued). "Perhaps the most studied species in this group, Bacteroides fragilis, has been shown to be protective against DSS colitis in mice by stimulating IL-10 expression." (PMID 33024049, 2020). "Colonization of GF IL-10−/− mice with Δeut E. faecalis plus SIHUMI consortia induced significantly increased colitis as compared to colonization with the WT E. faecalis plus SIHUMI." (PMID 32133003, 2020). "Alternatively, CD11c−CCR2−CX3CR1− macrophages or M2 macrophages induced by IL-4, IL-13, IL-10 or TGF-β show an anti-inflammatory profile in experimental colitis and are decreased in the colons of patients with active IBD." (PMID 31482438, 2020). "In a mouse model of IBD, the IL-10 KO mice model developing spontaneous colitis, germ-free mice infected with yersiniabactin-producing AIEC developed fibrosis." (PMID 32466328, 2020). "An increase of IL-10 by IL-35 treatment was already described in an acute DSS-induced colitis mouse model as well as in peripheral blood mononuclear cells from UC patients." (PMID 31955243, 2020). "IL10 can reduce antigen presentation, inhibit T cell activation and limit excessive inflammatory reactions in response to endotoxins, e.g. colitis or endotoxin shock." (PMID 33506093, 2020). "As obtained using longer administration periods, in the current experiment, the treatment with BC for 7 days reduced the increase of IL-10 gene expression in TNBS-induced colitis in mice." (PMID 32183497, 2020). "Sinapic acid treatment increased the serum levels of IL-4 and IL-10 in colitis mice and promoted the mRNA expression of these anti-inflammatory cytokines in the colons of colitis mice." (PMID 33312339, 2020). "Using a model of Helicobacter-induced IL-10-/- mouse of colitis, Yang and colleagues demonstrated that mice housed within different facilities developed colitis with characteristically different levels of inflammation." (PMID 33664728, 2020). "IL-2 knockout mice have dysregulated T cell functions and develop chronic immune mediated colitis in SPF mice, however these mice like the IL-10-/- mice discussed earlier fail to develop colitis under germ-free conditions." (PMID 33537028, 2020). "One study proposed that IL-17A plays suppressive roles in spontaneous colitis in conjunction with IL-10 through myeloid derived suppressor cell (MDSC) and inducible nitric oxide synthase (iNOS)." (PMID 32676080, 2020). "As with the other Helicobacter infections, H. hepaticus infection triggered colitis and tumorigenesis in IL10−/− mice." (PMID 32286276, 2020). "Histopathological hallmarks of colitis in Il10-/- mice are inflammatory cell infiltration of the lamina propria and submucosa, epithelial hyperplasia, mucin depletion, crypt abscesses, ulceration, and thickening of the intestinal wall." (PMID 33664727, 2020). "Oral supplementation with 2-fucosyllactose significantly decreased the severity of colitis in IL-10−/− mice, reducing the expression of IL-1β and IL-6 and increasing TGF-β expression and expansion of the propionate-producing commensal Ruminococcus gnavus." (PMID 32429359, 2020). "In fact, different species of the genus Lactobacillus have been shown to be effective in promoting the expression of Il-10 or in reducing the expression of adhesion molecules that promote leukocyte recruitment in an experimental colitis model." (PMID 32942624, 2020). "Inactivation of c-MAF in the Treg cells has been found to result in dysfunction of IL-10 production and such mice were prone to spontaneous colitis." (PMID 32670290, 2020). "Il10-/- mice on the C57BL/6 background readily develop moderate to severe colitis when their mucosal barrier is compromised by exogenous triggers such as infection with Helicobacter species or exposure to non-steroidal anti-inflammatory drugs (NSAIDs)." (PMID 32941525, 2020).
colitis (continued). "In mice, macrophages are considered one of the most important sources of IL-10 to maintain and minimize mucosal immunopathology by promoting Foxp3 expression in regulatory T cells (Treg) and their function during colitis." (PMID 32033338, 2020). "IL-10 is another cytokine produced by Treg cells with immunoinhibitory effects, which plays a significant role in the development of colitis." (PMID 32849906, 2020). "The cheese matrix intake further enhanced secretion of IL-10 during DSS-induced colitis, compared to the healthy group." (PMID 32156075, 2020). "Administration of the MSC-DCs in DSS-induced colitis mice causes colon tissue IL-6, IFN-γ, and TNF-α to decrease while Foxp3, IL-10, and TGF-β increase." (PMID 32256612, 2020). "Especially, secretion of the anti-inflammatory cytokine IL-10 by Treg cells has proven to be essential for maintaining intestinal tolerance, as evidenced by the development of spontaneous colitis upon genetic deletion of IL-10 selectively in Foxp3+ cells." (PMID 33193456, 2020). "NLRP3 KO mice were found to be susceptible to DSS- and 2,4,6-trinitrobenezene sulfonic acid-induced experimental colitis and had reduced levels of IL-1β, IL-10, and TGF-β." (PMID 33143375, 2020). "DSS-induced colitis increased the secretion of IL-10 and of TGFβ, which is consistent with the observed induction of these cytokines in UC patients." (PMID 32156075, 2020). "For example, monocolonization with Akkermansia muciniphila is sufficient to drive spontaneous colitis development in germ‐free IL10−/− mice." (PMID 32350866, 2020). "Although IL-10 level changes in inflamed colon tissues depend on the colitis model, the present study shows IL-10 levels were increased by DSS in the colon tissues of WT mice." (PMID 32365634, 2020). "In contrast, mice treated with BtLj displayed attenuated colitis, accompanied by a significant reduction in IL-1β and an increase in IL-10 transcripts." (PMID 32661259, 2020). "The concentration of IL-17 markedly reduced in the QCHS-treated DC group, whereas the mRNA and protein concentrations of IL-10 markedly increased in the QCHS-treated DC group compared with the experimental colitis model mice group." (PMID 32967687, 2020). "The resulting IL-10 secretion reduced various colitis parameters, with potential for clinical trials to treat colitis." (PMID 33251190, 2020). "Colonization of adult GF IL-10−/− mice with fecal microbiota from SPF WT mice induced mild colitis and immune activation by 1 week that progressed to severe inflammation after 5 weeks." (PMID 32133003, 2020). "In a colitis model, Ym1+Ly6Chi monocytes expand in the bone marrow during the recovery phase, produce high levels of IL-10 and contribute to the resolution of inflammation." (PMID 33329540, 2020). "In MafΔT mice, this additional source of IL-10 is lost and the threshold for the development of colitis decreases further." (PMID 32117317, 2020). "The production of IL-10 was increased in a mouse model of colitis induced by dextran sulfate sodium after BBR administration." (PMID 32231564, 2020). "Lactibiane iki contains two probiotic strains that have previously proved their capacity of increasing immunoregulatory cytokine interleukin (IL)-10 in vitro and of diminishing clinical severity in experimental colitis." (PMID 32272791, 2020). "PRCC-1301 EVs were administered to the piroxicam-induced chronic murine colitis model for 14 days using IL-10-/- mice." (PMID 33233771, 2020). "Colitis in Il10-/- mice is characterized by colonic inflammation that is transmural but discontinuous, forming “skip lesions” similar to what is observed in humans with CD." (PMID 32941525, 2020). "While DSS treatment initially triggered colitis in both IL10−/− and IL10+/− mice, colitis scores returned back to baseline in control IL10+/− mice, whereas they remained high in IL10−/− mice until the end of the 6-week experiment." (PMID 32286276, 2020).
colitis (continued). "The essential role of IL-10 in protecting from intestinal inflammation is undisputed as both humans and mice with defects in IL-10 signaling develop severe colitis that is dependent on microbial colonization." (PMID 31906479, 2020). "They indeed weakly respond to many different innate stimulations, constitutively express IL-10 and its receptor, participate in Treg cell expansion, and protect from colitis." (PMID 33681185, 2020). "Another study using AvCystatin, highlighted the role of IL-10 from regulatory macrophages (Mregs) in the suppression of the colitis conditions." (PMID 32486220, 2020). "Arrietaet al., using the IL-10 knockout colitis mouse model, showed increased small intestinal permeability that preceded the onset of the overt colitis that can be ameliorated by oral treatment with zonulin inhibitor AT-100152." (PMID 32051759, 2020). "Some models of colitis entirely depend on the presence of gut microbiota including IL-10−/− model of colitis." (PMID 32429195, 2020). "The development of colitis in the IL10–/– mice is dependent on the genetic background and intestinal microbiota." (PMID 32634481, 2020). "This led the investigators to examine the impact of the IBD microbiota on colitis-prone IL-10−/− mice." (PMID 32133003, 2020). "This is supported by previous studies showing that Sonic HH/GLI signaling can induce IL10 expression in a murine model of colitis and pancreatitis." (PMID 32615027, 2020). "IL-27 producing L. lactis proved more effective than both its IL-10 producing counterpart and systemic administration of IL-27 in colitis mouse models." (PMID 32296696, 2020). "Probiotic strains, just like lactic acid bacteria, have been suggested to increase the levels of anti-inflammatory cytokines, such as IL-10 in vivo colitis models." (PMID 33052226, 2020). "As colitis in Il10-/- mice is dependent on Th1 and Th17 immune responses, increased expression of IL4 can act as a negative regulator of inflammation." (PMID 33664727, 2020). "IL-10's protective function has been identified in many colitis models, including the DSS-induced colitis model and the CD45RBhi T cell transfer colitis model, which mimic ulcerative colitis (UC) and Crohn's disease, respectively." (PMID 32670290, 2020). "IL-2-/- and IL-10-/- mice developed spontaneous colitis, which highlighted the critical roles of cytokines in IBD." (PMID 33584726, 2020). "As a classic anti-inflammatory factor, IL-10 secretion was decreased for the downregulated function of Tfh10 cells in DSS-induced colitis." (PMID 32581849, 2020). "It was shown that this strain increased the production of IL-10 in the intestinal epithelium, contributing to the effectiveness against colitis." (PMID 32296696, 2020). "Our data showed that PRCC-1301 EVs downregulated NF-κB signaling pathways in colon tissues by suppressing phosphorylation of IκBα in DSS-induced and IL-10-/- colitis." (PMID 33233771, 2020). "They used E. faecalis, an organism shown to induce intestinal inflammation in monoassociated colitis-prone IL-10−/− mice, to examine the functional role of this bacterium within the inflammatory response and as a member of a complex bacterial community." (PMID 32133003, 2020). "DSS treatment significantly decreased the levels of IL-4 and IL-10 in the serum of the colitis mice." (PMID 33312339, 2020). "Immunological defect models, such as IL-10 knockout and sensitized Rag models had spontaneous colitis due to complicated imuno-pathological mechanisms." (PMID 32541827, 2020). "Tregs and IL-10 producing Tr1 cells have the potential to prevent or cure colitis, which is supported by a favourable safety profile in phase I clinical trials." (PMID 32617076, 2020). "Wogonin repelled the production of immunoglobulins and cytokines (such as IL-4, IL-5, and IL-10) from mesenteric lymphocytes in DSS-induced colitis in vivo." (PMID 32566686, 2020).
colitis (continued). "Results of the comparative transcriptomics analyses across DSS and IL-10 deficient mouse models, however, suggest that our TWD-enhanced DSS colitis model shares some similar transcriptional responses as observed in Il10-/- mice." (PMID 32093192, 2020). "E. coli Nissle has previously been engineered to deliver the angiogenesis inhibitor Tumstatin (Tum-5) to restrain murine melanoma; recombinant strains of L. lactis have been engineered to deliver interleukin 10 (IL-10) and Elafin to ameliorate colitis in mice." (PMID 32582668, 2020). "CD4+ T cell subsets in the colitis tissues were identified using qPCR—T-bet and Ifn-γ for Th1, Gata-3 and Il-4 for Th2, Rorγt and Il-17 for Th17, and Foxp3 and Il-10 for Treg subsets." (PMID 33092149, 2020). "Other popular models include TNBS–induced colitis, oxazolone-induced colitis, cell transfer models (e.g., adoptive T-cell transfer), and IL-10 knockout." (PMID 32354192, 2020). "The literature suggest that M2 macrophages can protect against colitis both by secreting immunosuppressive factors (such as IL-10) that promote tissue repair and by driving epithelial cell regeneration and proliferation." (PMID 32269253, 2020). "Neutralizing of IFNγ prevents the development of severe C. jejuni-mediated colitis in IL-10-/- mice." (PMID 33488580, 2020). "It is well known that the anti-inflammatory cytokine IL-10 is elevated in colitis patients and our study mirrored this effect upon DSS exposure." (PMID 31940911, 2020). "IL-1β protein levels were increased in IL-10 KO mice, but a caspase-1 inhibitor significantly improved spontaneous colitis in these mice." (PMID 33143375, 2020). "Both QCHS and QCHS-treated DCs improved colonic histopathology, diminished Th17 cell differentiation and inhibited IL-17 production while promoting CD4+CD25+Foxp3+ Treg differentiation and augmenting IL-10 and Foxp3 expression in colitis mice." (PMID 32967687, 2020). "It has been previously reported that EN reduces inflammation in murine IL-10−/− cell transfer colitis models." (PMID 32855978, 2020). "We thus detected the levels of IFN-γ and IL-10 in the spleens of mice with DSS-induced colitis after treatment with mSjci by flow cytometry." (PMID 33469451, 2020). "Promoting the generation of some anti-inflammatory cytokines (such as IL-4 and IL-10) has been shown to attenuate colitis in vivo." (PMID 33312339, 2020). "Another study also demonstrated that GPR4 deletion alleviates intestinal inflammation in the DSS-induced colitis and the IL10-/- spontaneous colitis mouse models." (PMID 33553219, 2020). "In this context, our study examined the dose-dependent effects of dietary fiber on immune cytokine production, histopathology and the gut microbiota in an Interleukin 10 (IL-10) knock out (IL-10−/−) murine colitis model." (PMID 32679670, 2020). "TAK-242 markedly alleviated DSS-induced colitis symptoms and colonic lesions by promoting IL-10 release, inhibiting IL-17 release, downregulating TLR4 and JAK2/STAT3 mRNA and protein expression and increasing JAK2/STAT3 phosphorylation." (PMID 32762699, 2020). "In mice with induced colitis, when treated with C. sinensis Stefin-1, the IL-10 levels were significantly increased in the spleen and MLN along with an increase in IL-10+ F4/80+ macrophages." (PMID 32486220, 2020). "A therapeutic strategy using single-chain human IL-27 suppressed several inflammatory cytokines, including IL-17, but promoted IL-10 secretion in a TNBS-induced mouse colitis." (PMID 32403220, 2020). "IL-10, an anti-inflammatory cytokine, plays a critical role in the homeostasis of the gut, which was illustrated by the finding that spontaneous colitis occurs in IL-10−/− mice." (PMID 33083147, 2020). "In view of its clear role in preventing colitis, supplementation of human recombinant IL-10 has been tried as a therapeutic approach for CD." (PMID 31906479, 2020).
colitis (continued). "These bacteria (such as B. cellulosilyticus DSM 14838) or their lysates induce abundant IL-10 in vitro and protect against colitis in a trinitrobenzenesulfonic acid (TNBS)-induced enteritis model." (PMID 33364945, 2020). "XylB treatments reversed the imbalance between pro- (IL-1β, TNF-α, and IL-17A) and anti-inflammatory (IL-10) cytokines in experimental colitis." (PMID 32429359, 2020). "Previous studies reported that spontaneous colitis was prevented in Il10−/− mice, Tcra−/− mice and HLA-B27 Tg rats under germ-free conditions or by microbiota deletion with antibiotics." (PMID 30753547, 2019). "Meanwhile, evidence has been put forth that IL-10 production in colitis can be stimulated by certain probiotics." (PMID 30915354, 2019). "In contrast, colitis development in Il10−/− mice is driven by an aberrant response of Th1 cells and exaggerated production of pro-inflammatory cytokines such as IFNγ, IL17, and IL12 to microbiota-derived antigens." (PMID 31396223, 2019). "In mouse models of colitis and allergic inflammation, Lactococcus lactis-expressing IL-10 treated inflammation and was safe when administered in a human phase I trial." (PMID 30642013, 2019). "To that end, we previously showed that total B cell depletion led to a break in tolerance as indicated by reduced numbers of Treg and the onset of spontaneous EAE in MBP-TCR transgenic mice and acceleration of colitis onset in Il10−/− mice." (PMID 30643147, 2019). "Meanwhile, IL-10, one of the best-studied anti-inflammatory cytokines, also contributed to the progress of colitis." (PMID 31182999, 2019). "In our study, we found that AL-1 increased the secretion of IL-10 dramatically in sera of DSS-induced colitis mice." (PMID 31687082, 2019). "Simultaneous colonization of IL-10−/− mice with E. coli and E. faecalis resulted in more aggressive colitis as compared to disease induced by each species individually." (PMID 31281321, 2019). "F. prausnitzii supernatant can inhibit NF-κB signaling of Caco2 cells and ameliorate 2,4,6-trinitrobenzene sulfonate sulphonic acid-induced colitis in mice by increasing IL-10 expressions." (PMID 31110701, 2019). "Given the fact that the PI3Kδ pathway is involved in IL-10-mediated immune suppression by B cells in vitro, we investigated the involvement of B cell PI3Kδ in T cell-mediated colitis in vivo." (PMID 31546615, 2019). "Of note, alpha-1-B glycoprotein (A1BG) was also decreased, whereas haptoglobin (HP), pregnancy zone protein (PZP), and hemopexin (HPX) were increased throughout the colitis progression in IL-10−/− mice." (PMID 30774653, 2019). "The anti-inflammatory effect of 2FL supplementation on colitis in Il10-/- mice was confirmed by measuring the changes in colon length in oligosaccharide-supplemented WT and Il10-/- mice." (PMID 31275292, 2019). "Mice of the DSS + PBS group lost weight over time, and weight loss in mice with colitis that were treated with M2 macrophages (DSS + IL-13-cell; DSS + IL-10-cell; and DSS + IL-1β-cell groups) was alleviated." (PMID 31749791, 2019). "Conversely, the level of anti-inflammatory cytokine IL-10 decreased significantly (comparing with the control group) in the colitis group." (PMID 31726738, 2019). "The results confirmed that Gls1 promotes Th1‐ and Th17‐cell responses, and BPTES treatment can inhibit Th1 and Th17 responses in experimental colitis in IL‐10−/− mice." (PMID 31211512, 2019). "To understand the mechanism that underlies the alleviation of DSS-induced colitis in mice after treatment with EPS-1, we examined the levels of Th1 pro-inflammatory (TNF-α, IL-6, and IFN-γ) and anti-inflammatory (IL-4 and IL-10) in colon tissues." (PMID 30708992, 2019). "Deletion of IL-10 in T-regs induces spontaneous colitis, highlighting the physiological importance of T-reg-derived IL-10." (PMID 31547627, 2019).